RNU6-217P (RNA, U6 small nuclear 217, pseudogene)
Gene: Small nuclear RNA gene on chromosome 3 (77,811,741 to 77,811,844, reverse strand). Ensembl gene ENSG00000206891.
Homologues: Orthologues: chimpanzee U6 (100% identical), macaque U6 (91% identical). Paralogues in human: RNU6-1060P (88% identical), RNU6-116P (88% identical), RNU6-15P (88% identical), RNU6-790P (88% identical), RNU6-125P (87% identical), RNU6-33P (87% identical), RNU6-672P (87% identical), RNU6-1 (86% identical), RNU6-19P (86% identical), RNU6-2 (86% identical), RNU6-3P (86% identical), RNU6-480P (86% identical), and 1285 more.